RNU6-1319P (RNA, U6 small nuclear 1319, pseudogene)
Gene: Small nuclear RNA gene on chromosome 1 (223,976,146 to 223,976,249, reverse strand). Ensembl gene ENSG00000212157.
Homologues: Orthologues: chimpanzee U6 (100% identical), macaque U6 (92% identical), pig U6 (83% identical), pig U6 (79% identical), dog U6 (78% identical). Paralogues in human: RNU6-241P (100% identical), RNU6-747P (100% identical), RNU6-1076P (99% identical), RNU6-1100P (99% identical), RNU6-1118P (99% identical), RNU6-1217P (99% identical), RNU6-355P (99% identical), RNU6-447P (99% identical), RNU6-785P (99% identical), RNU6-791P (99% identical), RNU6-860P (99% identical), U6 (99% identical), and 1287 more.